BAG6 (BAG cochaperone 6)
Diseases named in the same sentence as BAG6 in open-access papers (continued):
Sharing a sentence is not in itself a finding about the gene and the disease.
tumor (continued). "Deletion of BAG6 strongly accelerated tumor growth in an MC-dependent manner and this effect was rescued upon in vivo inhibition of the EV release." (PMID 38942797, 2024). "Consistent with in vitro experiments, overexpression of endogenous BAG6 markedly attenuated both the tumour size and weight in vivo." (PMID 37700495, 2023). "B7-H6 is recognized by the NKp30 receptor, as are BAT3/ BAG6 and galectin 3—all of which are commonly expressed on tumour cells." (PMID 36831514, 2023). "When BAG6 was ablated and this pathway was disrupted, a distinct EV subtype was released, recruiting tumor-promoting neutrophils to the pre-metastatic niche, resulting in the progression of tumors and metastasis." (PMID 37158964, 2023). "NKp30 ligands include B7-H6 and the HLA-B-associated transcript 3 protein (BAT3), also known as BAG6, both able to promote NK cell cytotoxicity against tumor cells and soluble galectin-3 implicated in NK cell tumor evasion." (PMID 37313439, 2023). "Ligands for NKp30, including BAG6 and B7-H6, are upregulated in virus-infected and tumor cells but rarely detectable on healthy cells." (PMID 33671836, 2021). "EVs presenting BAG6 (EV-BAG6) activate NK cells via the NKp30–BAG6 axis; however, BAG6-positive vesicles were hardly detectable in the serum of tumor patients." (PMID 33671836, 2021). "This renders BAG6 a potential therapeutic tool to specifically interfere with the biogenesis of exosomes, which can re-program the biological activity of tumor-cell derived EVs into anti-cancer moieties." (PMID 31534536, 2019). "Regulation of NK cell activity depends on the presentation of BAG6 on the surface of EVs released in response to cellular stress, which triggers NK cell-mediated anti-tumor activity in vitro and in vivo." (PMID 31534536, 2019). "Tumor exosomes have been found to frequently exert immunostimulatory effects through the expression of BAG6/BAT3, a ligand for NK cell NKp30 activating receptor, normally expressed in DCs." (PMID 31130953, 2019). "NKp30 recognizes the tumor antigens B7-H6 and BAG6 (also known as BAT3) but only B7-H6 has been involved in tumor clearance due to its restricted expression on malignant cell lines." (PMID 25961317, 2015). "Here, we compared the influence of tumour cell-derived soluble and vesicle-associated ligand BAG6(BAT3) engaging the activating NK cell receptor NKp30 on NK cells in CLL." (PMID 26082317, 2013). "Material and methods: We quantified soluble and vesicle-associated BAG6 in the serum of CLL patients and healthy donors and analysed the release of BAG6 from tumour cell lines and primary CLL cells." (PMID 26082317, 2013). "BAG6, a nuclear protein, is released in response to stress signals from tumor and dendritic cells." (PMID 39752457, 2025). "Thus, Bag6 deficiency caused EV-dependent and MC-mediated changes in both, tumor cells and the TME fueling tumor progression." (PMID 38942797, 2024). "This demonstrated the crucial role of EVs in the Bag6 phenotype and tumor progression." (PMID 38942797, 2024). "Soluble BAG6 can be released from heat‐shocked tumor cells and inhibit NK cell cytotoxicity, indicating that BAG6 may be a mediator of tumor immune escape." (PMID 35499292, 2022). "Three specific cellular ligands of NKp30 have been identified so far: BAG6, B7-H6, and galectin-3, all of which could be found on the tumor surface, but while BAG6 and B7-H6 activate NK cell cytotoxicity, galectin-3 blocks it completely." (PMID 34829829, 2021).
tumor (continued). "In particular, on tumor cells, NCRs may recognize intracellularly localized proteins, such as BAT3/BAG6 and PCNA, that may be expressed at the cell surface of stressed or cancer cells, or cell surface molecules, such as B7-H6 and 21spe-MLL5." (PMID 33321719, 2020). "However, NKp30 is a pseudogene in the murine system and not expressed as a functional receptor 16, suggesting that the anti-tumor activity of BAG6-presenting EVs in mouse models depends on NKp30-independent acitivities." (PMID 31534536, 2019). "Given the function of intracellular BAG6 in many crucial biological processes such as protein targeting and degradation 17, we hypothesize that its anti-tumor activity relies on BAG6-dependent recruitment of other effector molecules to EVs." (PMID 31534536, 2019). "Human leukocyte antigen-B-associated transcript 3 (Bat3), also known as BAG-6, could be considered a DAMP due to its release from tumor cells." (PMID 25699048, 2015). "It has been shown that BAT3/BAG6 can be released from tumor cells in response to stress signals." (PMID 24244368, 2013). "In contrast, a strong expression of BAT3/BAG6 was found in tumor cells of THRLBCL (10/10 cases), but a somewhat weaker expression was also observed in different variant patterns of NLPHL (10/10 and 8/10 cases for patterns A and C, respectively) and THRLBCL-like NLPHL (7/10 cases)." (PMID 24244368, 2013). "The current study revealed a so far unknown tumor-suppressing activity of BAG6 in PDAC." (PMID 38942797, 2024). "Unlike another NKp30 ligand, BAT3 (HLA‐B‐associated transcript 3, also identified as BAG6, BCL2‐associated athanogene 6),which normally acts as an intracellular molecular chaperon, B7-H6 is located on the cell surface and upregulated in stressed and tumor cells." (PMID 38035117, 2023). "NKp30 recognizes BAT3/BAG6 and B7-H6; NKp44 recognizes NKp44 ligand, a unique splice variant isoform of MLL5 protein; NKp46 recognizes vimentin; and each of these NCRs also recognizes particular heparan sulfate glycosaminoglycans that are uniquely expressed in tumor microenvironments." (PMID 31071196, 2019). "We next assessed the NSCLC tumor biopsy from patient 006 for expression of the cognate ligands for NKGD2 (i.e., MICA/B), DNAM-1 (i.e., CD112), and NKp30 (i.e., B7H6 and BAG6)." (PMID 39903538, 2025). "Here, we showed that USP19 binds to BAG6 and decreases BAG6 ubiquitination, which prevents BAG6 from being degraded in TNBC tumour tissue and BC cells." (PMID 37700495, 2023). "When presented with the natural cytotoxicity triggering receptor 3 (NCR3)-ligand BAG cochaperone 6 (BAG6), NK cells quickly dispose of tumor cells." (PMID 37822925, 2023). "Of note, tumor cells from ORs and SORs were the most prominent sources of ALCAM on effector T cells and BAG6 on NK cells, respectively." (PMID 36380017, 2022). "Discovering cellular ligands of the NCR still represents a great challenge, and only few cellular and viral ligands have been identified, such as the NKp30 ligands BAT3 (or BAG6) and B7-H6, which are expressed or released by tumor cells." (PMID 24744763, 2014).
tumor (continued). "The absence of Bag6 allowed the establishment of a tumor-promoting TME characterized by reduced infiltration of T cells and enhanced abundance of fibroblasts, known to restrict or support PDAC progression, respectively." (PMID 38942797, 2024). "The s.c. tumor growth in the absence of Bag6 was significantly increased according to the volume and weight." (PMID 38942797, 2024). "B7-H6, BAG6/BAT3 and galectin -3 belong to the common tumor cell ligands of NKp30 protein." (PMID 37078002, 2022). "In contrast to B7-H6, the NKp30 ligand BAG6 is not a classical surface molecule but a nuclear protein, which is released upon stress signals via extracellular vesicles (EVs) from tumor and dendritic cells." (PMID 33671836, 2021). "In addition, shedding of MIC-A (NKG2D ligand) or of BAT3/BAG6 and B7H6 (ligands of NKp30), is a tumor escape mechanisms commonly reported." (PMID 32218226, 2020). "Genetic ablation of BAG6 and disruption of this pathway led to the release of a distinct EV subtype, which failed to suppress metastasis but recruited tumor-promoting neutrophils to the pre-metastatic niche." (PMID 31534536, 2019). "In contrast, a soluble form of BAT3/BAG6 has been found at high levels in the plasma of CLL patients and can suppress NK cytolytic responses, apparently by blocking recognition of this and other ligands on tumor cells." (PMID 28424697, 2017). "In addition, BAG6/BAT3, a nuclear protein localized at the plasma membrane or on exosomes of tumor cells, has also been assigned as an NKp30 ligand." (PMID 24715892, 2014). "On the other hand, dendritic cell-secreted BAG6 could promote both survival and cytokine release of NK cells by binding to NKp30 and directly signal to CD8 T-cells via CXCL16-CXCR6, thereby generating an anti-tumor feedforward loop." (PMID 39656086, 2024).
cancer (21 papers, 2012 to 2025). A tumor composed of atypical neoplastic, often pleomorphic cells that invade other tissues. "Therefore, we studied the role of Bcl-2-associated-anthanogene 6 (BAG6), a regulator of EV biogenesis for cancer progression." (PMID 38942797, 2024). "It has been shown that NKp30 is blocked by exosomal and soluble BCL-2-associated athanogene-6 (BAG6) which are released by cancer cells; however, during infection with certain viruses, soluble influenza haemagglutinin (HA) and pp65 take similar effect to block NKp30 or NKp46." (PMID 24138752, 2013). "In our current investigation, we have discovered that DERL2 functions to stabilize BAG6, potentially contributing to cancer progression." (PMID 37815698, 2024). "However, the precise identity of the critical BAG6 modulators in cancer progression remains elusive." (PMID 37815698, 2024). "One of the hypotheses underlying the mechanisms involved in NKp30 down regulation in AML, a chronic exposure to Nkp30 ligands such as B7-H6 or BAG6 has been proposed and demonstrated in other cancers." (PMID 28548938, 2017). "Noteworthy, the discovery of B7-H6 and BAG6, ligands for NKp30, included the detection of soluble forms, which may compete for cell–cell interaction with membrane-bound ligands, although only soluble/exosome-bound BAG6 has been detected in a cancer situation." (PMID 24715892, 2014). "Our findings indicated that HLA-E-positive cancer cells, mesothelial cells, and aDC2 regulate MAIT cells through the BAG6-NCR3 axis, with high BAG6 concentrations correlating with worse patient prognosis." (PMID 40959273, 2025).
infection (8 papers, 2012 to 2024). The state of being infected such as from the introduction of a foreign agent such as serum, vaccine, antigenic substance or organism. "BAG6 is a key protein associated with activation and cell death of antigen presenting cells during infection." (PMID 24625963, 2014). "In the present study, we have also shown that infection of macrophages with heat-killed M. tuberculosis (H37Rv) led to up-regulation of FAM46A RNA while a previous report also showed up-regulation of BAG6 RNA in macrophages upon stimulation with ESAT protein of M. tuberculosis." (PMID 24625963, 2014).
hematologic malignancies (2 papers, 2019 to 2020). "NK cell dysfunctions have been observed in various hematologic malignancies, including chronic lymphocytic leukemia (CLL) through soluble ligand BAG6/BAT3." (PMID 32537468, 2020).
neurodegenerative disease (1 paper, 2024). A disorder of the central nervous system characterized by gradual and progressive loss of neural tissue and neurologic function. "This included two known proteins associated with MERCS, MFN2 and TOMM40, as well as neurodegenerative disease-associated genes such as WIPI2, CLASRP, BAG6, SOD1 and FUS which increase MERCS and MTCH2 and PARL which decrease MERCS." (PMID 38467609, 2024). "Together, these data may suggest additional roles for BAG6 in the aetiology of neurodegenerative diseases." (PMID 38467609, 2024). "Both BAG6 and HSP70 have been associated with a range of neurodegenerative diseases." (PMID 38467609, 2024).
BAG6 also shares sentences with these, for which no sentence is quoted: hepatocellular carcinoma (5 papers); Autoimmunity (3); osteosarcoma (3); anxiety disorder (2); graft versus host disease (2); neurological diseases (2); adenocarcinoma (1); allergic disease (1); Anxiety (1); avian influenza (1); breast carcinoma (1); diabetic retinopathy (1); endocrine disorder (1); glioma (1); HCMV infection (1); influenza (1); leukemia (1); liver cancer (1); lung adenocarcinoma (1); mental illness (1); multiple myeloma (1); myasthenia gravis (1); myocardial infarction (1); neuroblastoma (1); preeclampsia (1); systemic lupus erythematosus (1); teratocarcinoma (1); thrombotic microangiopathy (1); triple-negative breast carcinoma (1); type 1 diabetes mellitus (1).
A further 2 diseases each share a sentence with BAG6 in 1 paper.